PSMC2 (proteasome 26S subunit, ATPase 2)
Diseases named in the same sentence as PSMC2 in open-access papers (continued):
Sharing a sentence is not in itself a finding about the gene and the disease.
gallbladder cancer (2 papers, 2021 to 2022). "GNG4 was also explored as a downstream target of PSMC2 in gallbladder cancer (GBC)." (PMID 36299585, 2022).
kidney cancer (2 papers, 2020 to 2022). Primary or metastatic malignant neoplasm involving the kidney. "At the tissue level, the expression of PSMC2 in kidney cancer tissue was significantly higher than that in normal kidney tissue." (PMID 32972417, 2020). "Besides, PSMC2 is highly expressed in kidney cancer cells and has a tumor-promoting effect on kidney cancer." (PMID 35256584, 2022). "By combining PSMC2 RNA expression data of common renal cancer cell lines and tumor formation data of nude mice, the correlation between PSMC2 and invasiveness can be clarified, at the same time, the expression of PSMC2 in kidney cancer tissue was higher than that in normal kidney tissue." (PMID 32972417, 2020). "A total of 1019 cell lines related to PSMC2 RNAseq were obtained from the CCLE database, including 32 kidney cancer cell lines." (PMID 32972417, 2020). "At the same time, the average RNA expression of PSMC2 in renal cancer cells with tumorigenicity was higher than that of non-tumorigenic kidney cancer cells, but the data were too few to judge statistical significance." (PMID 32972417, 2020).
brain glioma (1 paper, 2022). A malignant glioma that involves the brain. "In order to verify the expression of PSMC2 in brain gliomas, we selected a total of 60 samples in this study." (PMID 35287689, 2022).
cholangiocarcinoma (1 paper, 2021). A carcinoma that arises from the intrahepatic biliary tree (intrahepatic cholangiocarcinoma) or from the junction, or adjacent to the junction, of the right and left hepatic ducts (hilar cholangiocarcinoma). "Relationship between PSMC2 expression and tumor characteristics in patients with cholangiocarcinoma." (PMID 34499615, 2021). "Expression patterns of PSMC2 in cholangiocarcinoma tissues and normal tissues revealed in immunohistochemistry analysis." (PMID 34499615, 2021).
chronic pancreatitis (1 paper, 2019). A chronic inflammatory process causing damage and fibrosis of the pancreatic parenchyma. "Of the 40 tumors evaluated in this study, 28 (70%) were strongly cytoplasm positive for PSMC2 expression in cancer cells, while it was negative in all the chronic pancreatitis tissues." (PMID 31598166, 2019).
co-infection (1 paper, 2021). "Moreover, the co-infection of shPLAU and shPSMC2 potentiate the inhibition effects of both PLAU and PSMC2 knockdown." (PMID 34244472, 2021).
glioblastoma (1 paper, 2025). The most malignant astrocytic tumor (WHO grade IV). "Among which, CDC73, PSMC2, SOCS3, and ETV4 were substantially upregulated; whereas PLK2 and LMO7 were substantially downregulated in glioblastoma cells than that in control." (PMID 41318472, 2025).
heart failure (1 paper, 2022). Inability of the heart to pump blood at an adequate rate to meet tissue metabolic requirements. "Proteasome 26S subunit, ATPase 2 (PSMC2) and proteasome 20S subunit Alpha 4 (PSMA4) identified by a CRISPR study were associated with many genetic risks of diseases, ranging from heart failure to MDD." (PMID 35903362, 2022).
lymph node metastasis (1 paper, 2022). "Across all six PSMC genes, only PSMC2 and PSMC4 exhibited a significant correlation with lymph node metastasis stage and neoplasm disease stage (p < .05), and groups with PSMC2 and PSMC4 overexpression had a higher number of patients with advanced lymph node metastasis and neoplasm disease stages." (PMID 36699466, 2022).
Osteoblastoma (1 paper, 2017). A rare benign bone-forming neoplasm usually arising from the spine. "Our tissue microarrays data revealed PSMC2 was highly expressed in all the chondroblastic, osteoblastoma-like, telangiectatic and fibroblastic cases and approximate 60% incidence of strong positive PSMC2 expression was detected." (PMID 27888613, 2017).
pancreatic adenocarcinoma (1 paper, 2019). "We conducted cDNA microarray analysis by using the Oncomine database to explore gene expression of PSMC2 in pancreatic adenocarcinoma." (PMID 31598166, 2019). "Our analysis revealed that PSMC2 was over-expressed in pancreatic adenocarcinoma, as compared to that in normal tissue." (PMID 31598166, 2019). "Here, we evaluated PSMC2 expression in pancreatic adenocarcinoma using IHC for the first time and conducted cDNA microarray analysis by using the Oncomine database to explore gene expression of PSMC2 in pancreatic adenocarcinoma tissues." (PMID 31598166, 2019).
renal carcinoma (1 paper, 2020). A carcinoma arising from the epithelium of the renal parenchyma or the renal pelvis. "We also analyzed the PSMC2 in the hub gene and found that overexpression of PSMC2 in various cancers is associated with poor prognosis, clarified its value as a prognostic factor and therapeutic target for renal cancer." (PMID 32972417, 2020). "At the same time, PSMC2 can be used as a poor prognostic indicator for renal cancer patients." (PMID 32972417, 2020). "Therefore, PSMC2 is expected to become a prognostic factor and therapeutic target for renal cancer." (PMID 32972417, 2020).
renal cell carcinoma (1 paper, 2020). "In renal cell carcinoma patients, PSMC2 is a poor prognostic factor for OS (HR = 1.78, 95% CI = 1.32–2.4, P < 0.001)." (PMID 32972417, 2020). "Indirect evidence at the cellular and tissue level suggests to a certain extent that PSMC2 plays a role in promoting tumors in renal cell carcinoma." (PMID 32972417, 2020).
sarcoma (1 paper, 2023). A usually aggressive malignant neoplasm of the soft tissue or bone. "Particularly, the expression levels of other proteasome pathway genes, including PSMC1, PSMB6, PSMC2, and PSMB10 seemed to be differentially expressed in MFS/US sarcomas." (PMID 37185612, 2023).
cancer (25 papers, 2014 to 2025). A tumor composed of atypical neoplastic, often pleomorphic cells that invade other tissues. "We note that PSMC2 has been linked to CRC cancers, but its interactions with other genes haven’t been reported." (PMID 38243058, 2024). "It has been reported that PSMC2, as the number one gene of cancer risk caused by partial loss due to the change of copy number, is related to cell proliferation and survival." (PMID 35287689, 2022). "listed PSMC2 as the highest-ranked gene of CYCLOPS (Copy-number alterations Yielding Cancer Liabilities Owing to Partial losS), which represents a special subset of essential genes related to the activity of cancer cells." (PMID 33902600, 2021). "Proteasome 26S subunit ATPase 2 (PSMC2) is the highest ranked candidate among the Copy-number alterations Yielding Cancer Liabilities Owing to Partial loss (CYCLOPS) genes, which are a special subset of essential genes involved in cancer cell viability." (PMID 33718159, 2021). "Proteasome 26S subunit ATPase 2 (PSMC2) plays a pathogenic role in various cancers." (PMID 33718159, 2021). "Moreover, the levels of several familiar key molecules in cancer-associated signaling pathways were detected using western blotting as a means to further illustrate the regulatory mechanism of PSMC2 on GBC." (PMID 34016944, 2021). "Moreover, the interaction network of PSMC2 with those cancer associated genes was constructed." (PMID 27888613, 2017). "Evidence from other cancers also indicated the positive role of PSMC2 knockdown in tumor progression." (PMID 41318472, 2025). "A pan-cancer analysis has suggested that PSMC2 serves as a reliable prognostic biomarker for predicting the response to immunotherapy." (PMID 41318472, 2025). "The frequency of partial genomic deletions of PSMC2 is reported to be 0.10 in 3131 cancers of multiple cancer types, indicating that cancer cells are highly dependent on the remaining PSMC2." (PMID 35287689, 2022). "Recent studies have revealed that some proteasome-related genes, such as PSMA3 and PSMC2, can promote the progression of malignant biliary tumors and act as potential biomarkers to predict prognosis." (PMID 36386204, 2022). "PSMC2, a key member of the 19S RP, a component of the 26S proteasome complex, has been studied in various cancers." (PMID 33718159, 2021). "Although PSMC2 was regarded as a novel synthetic lethal interaction relevant to human cancer, the functional validation and mechanism research for PSMC2 in BC is still unclear." (PMID 34244472, 2021). "Previous studies showed that PSMC6 promotes osteoblast apoptosis and cancer cell proliferation, while PSMC2 inhibits apoptosis." (PMID 34329194, 2021). "The expression of PSMC2 was significantly upregulated in human SKCM samples compared with the normal para-cancer skin tissues." (PMID 34716318, 2021). "Despite that PSMC2 is considered to be a newly discovered gene closely related to human cancer, its expressional characteristics and functional value in HCC is pending to be explored." (PMID 34413286, 2021). "The Cancer Genome Atlas (TCGA) database was used to analyze the expression of PSMC2 in SKCM and its impact on prognosis." (PMID 34716318, 2021). "At the same time, considerable research efforts have identified the important role of PSMC2 in some human cancers." (PMID 34413286, 2021). "To do this, we investigated the influence of PSMC2 depletion or the overexpression of several established cancer-related molecules in PC-3 cells by western blotting." (PMID 33902600, 2021). "Despite that PSMC2 is identified as a newly discovered cancer-related gene, little is concerning the expressional correlation and functional importance of PSMC2 in CCA." (PMID 34499615, 2021). "Although PSMC2 was regarded as a novel synthetic lethal interaction relevant to human cancer 13, the functional validation and mechanism discovery for PSMC2 in malignancies originating from the mesenchymal tissue is completely unclear." (PMID 27888613, 2017).
cancer (continued). "Silencing of another proteasome subunit, proteasome 26S subunit ATPase (PSMC2), remarkably reduced hepatocellular, prostate, breast, and gastric cancers viability, migration and invasion capacity, while promoting cell-cycle arrest and consequently apoptosis in these cell lines." (PMID 37529110, 2023). "Among them, PSMC2 was reported to be the highest-ranked one with potential role in human cancers." (PMID 33902600, 2021). "However, the other subunits of proteasome, such as PSMD3, PSMC2, and PSMD4, were upregulated in several cancers and associated with prognosis." (PMID 34239933, 2021). "It was demonstrated that some genomic deletions of PSMC2 were observed in more than 3000 tumors, which made the cancer cells highly dependent on the remaining PSMC2, and further indicated that PSMC2 could be used as a potential target for cancer treatment." (PMID 33902600, 2021). "Previous studies have also confirmed the important role of PSMC2 in some human cancers." (PMID 33902600, 2021). "In addition, PSMC2 genome deletions have been found in more than 3000 types of tumors, making the remaining PSMC2 particularly important for cancer cells." (PMID 34016944, 2021). "Moreover, accumulating evidence has suggested the regulatory function of human cancers by Survivin, which is a new member of anti-apoptotic protein family and whose expression was found to be decreased by PSMC2 knockdown in this work." (PMID 34499615, 2021). "PSMC2 is ranked as the top among 56 candidate genes in the Copy number alterations Yielding Cancer Liabilities Owing to Partial losS (CYCLOPS) genes, indicating the essential importance of PSMC2 in cancer cell viability." (PMID 34413286, 2021). "We determined expression levels of thirty-eight genes related to cancer that might be markedly regulated by PSMC2." (PMID 27888613, 2017). "Previous studies identified the important role of PSMC2 during certain human cancer." (PMID 27888613, 2017). "The observation indicated that partial genomic loss of PSMC2 was sought among more than 3000 tumors, rendering a high dependence of cancer cells on the remaining PSMC2 and further suggested PSMC2 could be regarded as a potential target for treating cancer." (PMID 27888613, 2017). "Moreover, the gene microarray indicated knockdown of PSMC2 notably changed a number of genes, especially some cancer related genes including ITGA6, FN1, CCND1, CCNE2 and TGFβR2, and whose expression changes were further confirmed by western blotting." (PMID 27888613, 2017). "However, research on PSMC2 is limited to functional experiments, and no studies have investigated the underlying mechanisms of the function of PSMC2 in cancer." (PMID 33718159, 2021). "All these outcomes indicated that PSMC2 may be a wide-range tumor promotor in human cancers." (PMID 34294689, 2021). "However, limited data is available concerning the functional significance of PSMC2 in cancer cell growth, and whether it plays a role in pancreatic carcinogenesis remains unknown." (PMID 31598166, 2019). "First, we showed that PSMC2 was ubiquitously expressed in SW1990, PANC-1 and AsPC-1pancreatic cancer cell lines." (PMID 31598166, 2019). "Not surprisingly, the role of PSMC2 in a number of human cancers has also been verified in the previous studies." (PMID 34016944, 2021). "Although PSMC2 has been recognized to be closely related to human cancer, its relationship with GBC has not been confirmed." (PMID 34016944, 2021). "Nevertheless, functional validation and mechanistic studies for PSMC2 in cancers have been lacking." (PMID 31598166, 2019). "Interestingly, we discovered that PSMC genes were overexpressed in a subtype-specific manner: specifically, PSMC1, PSMC2, PSMC3, PSMC4 were highly expressed in the triple-negative subtype, PSMC5 in HER-2, and PSMC6 in luminal cancer." (PMID 34329194, 2021).
tumor (23 papers, 2017 to 2025). "The statistical analysis of the association between PSMC2 expression and tumor characteristics of HCC patients was also employed to clarify the effects of PSMC2 on HCC development and progression." (PMID 34413286, 2021). "The correlation analysis between PSMC2 and tumor characteristics showed significant association between PSMC2 expression and tumor grade." (PMID 34294689, 2021). "We also discovered the significant association between PSMC2 expression and tumor infiltrate as well as tumor stage." (PMID 34413286, 2021). "First, the association between PSMC2 expression and tumor grade of GBC was determined, which has important clinical significance." (PMID 34016944, 2021). "Furthermore, our data indicated that elevated expression of PSMC2 is significantly associated with a larger tumor size and with poor OS and DFS." (PMID 33718159, 2021). "Because the expression of PSMC2 was associated with tumor size, we assessed whether PSMC2 affected the apoptosis and proliferation of HCC cells." (PMID 33718159, 2021). "Moreover, statistical analysis showed that GNG4 expression was also significantly associated with tumor grade and patient’s prognosis, which was similar to PSMC2." (PMID 34016944, 2021). "TCGA multi-tumor screening and survival analysis were combined to explore the differential expression of PSMC2 in multi-tumor." (PMID 35287689, 2022). "The results of immunohistochemical staining indicated that was PSMC2 downregulation inhibited Ki67 expression, which further suggested that PSMC2 knockdown inhibited tumor cell proliferation." (PMID 35256584, 2022). "PSMC2 also played a role in tumor progression by regulating the expression of some tumor-related genes." (PMID 35256584, 2022). "Gene-set enrichment analysis of PSMC2 co-expression genes was carried out to predict the molecular mechanism of their regulation of tumor cell phenotypes, and the analysis results were verified by flow cytometry and Western blot." (PMID 35287689, 2022). "Spearman correlation analysis determined that the expression of PSMC2 was positively correlated with pathological stage, Tumor Infiltrate, Ki67 expression and age." (PMID 35256584, 2022). "Next, we analyzed the correlations between PSMC2 expression and characteristics of HCC and found that high PSMC2 protein expression was significantly correlated with tumor diameter (P = 0.002) and sex (P < 0.013)." (PMID 33718159, 2021). "Meanwhile, the reduced number and lighter weight of solid tumors in the shPSMC2 group also suggested that tumor growth decreased upon the silencing of PSMC2 (P < 0.001)." (PMID 34016944, 2021). "Emerging evidence has declared that Proteasome 26S subunit ATPase 2 (PSMC2) is involved in tumor progression." (PMID 34244472, 2021). "Univariate Cox regression analysis suggested that PSMC2 expression, tumor size, and tumor-node-metastasis (TNM) stage were significant prognostic factors for HCC patients' OS and DFS." (PMID 33718159, 2021). "The suppression of tumor growth in vivo by PSMC2 knockdown was also showed by using mice xenograft models." (PMID 33902600, 2021). "Based on these intriguing results, this is the first time ever that PSMC2 is pinpointed as a tumor promotor to interfere HCC development and progression via interacting with ITGA6 directly." (PMID 34413286, 2021). "The averaged tumor weight of the shCtrl mice was significantly heavier than that of the silencing PSMC2 group." (PMID 34244472, 2021). "In this study, the results of immunohistochemistry analysis showed the upregulation of PSMC2 in CCA tissues compared with normal tissues, which was statistically analyzed to be associated with CCA tumor grade." (PMID 34499615, 2021). "In conclusion, these results clearly demonstrate that high PSMC2 expression enhances tumor growth in vitro and in vivo." (PMID 33718159, 2021).